VHL (von Hippel-Lindau tumor suppressor)
Diseases named in the same sentence as VHL in open-access papers (continued):
Sharing a sentence is not in itself a finding about the gene and the disease.
Renal cyst (38 papers, 2007 to 2026). A fluid filled sac in the kidney. "This is because, while PTEN inactivation alone is insufficient in causing renal cysts, in the presence of a VHL-null genetic background, it increases renal cysts and tumours in mice." (PMID 34828368, 2021). "Clear-cell RCC, PC (less often PGL and rarely HNPGL), and retinal and central nervous system hemangioblastomas (or the presence of pancreatic or renal cysts) should prompt genetic testing for VHL mutations." (PMID 28973655, 2017). "Patients with VHL disease have inherited mutations of VHL and renal cyst and/or tumors develop when these individuals undergo somatic inactivation or loss of the remaining wild-type VHL allele." (PMID 25180793, 2014). "Patients with VHL deficiency develop ccRCCs that are often preceded by pre-neoplastic renal cysts and mice deficient in VHL in the proximal tubule epithelium only develop low levels of renal cysts, demonstrating the requirement of other oncogenic events." (PMID 25277181, 2014). "The current view is that loss of VHL is sufficient for renal cyst formation, but that additional genetic lesions are required for subsequent degeneration of a renal cyst into ccRCC." (PMID 23628112, 2013). "Foci of RCC can also be seen in the context of simple renal cysts, and VHL deficiency can also be observed in the cystic epithelium, supporting the hypothesis of cysts as precursor lesions of ccRCC in VHL disease." (PMID 36358771, 2022). "Moreover, germline inactivation of the VHL gene, associated with the von Hippel-Lindau syndrome, is accompanied by a high frequency of renal cysts, which only occasionally develop into ccRCC18." (PMID 27491826, 2016). "The expression of Epo in RCC and renal cysts may result from VHL gene deficiency through the HIF-1 pathway." (PMID 23833638, 2013). "In conjunction with von Hippel-Lindau (VHL) gene deficiency, the co-expression of Epo and EpoR in renal cysts and tumors may reflect developmental arrest in immature mesenchymal cells." (PMID 23833638, 2013). "A case of a female patient was also described; she had adrenal pheochromocytomas that were removed at the ages of 11 and 18, and her father had a renal cyst and an epididymal cystadenoma due to VHL somatic mosaicism." (PMID 40141393, 2025). "On the other hand, HIFα plays a major role in mediating the effects of VHL on the primary cilium in the case of renal cysts." (PMID 39234399, 2024). "Germline heterozygous pathogenic variants in the Von Hippel-Lindau (VHL) gene is the most common genetic cause of RCC, where renal cysts often precede tumorigenesis." (PMID 38292052, 2023). "A number of tumor suppressor genes that have established roles in renal tumorigenesis, namely VHL, TSC1, TSC2 and FLCN, also predispose to renal cyst formation, a common hallmark of ciliopathy syndromes." (PMID 23369289, 2013). "Recent studies have focused on a VHL role in earlier stages of renal tumor development, namely renal cyst formation." (PMID 17598890, 2007). "The endothelial cells of BV expressed FSHR1 in 100% of VHL-patients with ccRCC and renal cysts." (PMID 41024941, 2025). "Their study found that cells lacking functional VHL failed to develop cilia, leading to disrupted ciliogenesis, which is linked to renal cyst formation and the development of renal cell carcinoma." (PMID 40277920, 2025). "Similar to ARP-T1, some cancer-associated mutations result in shorter cilia or faster ciliary resorption Von Hippel-Lindau (VHL) disease is characterized by the development of premalignant renal cysts, and arises because of functional inactivation of VHL tumor suppressor protein (pVHL)." (PMID 33972689, 2021). "Further study of the VHL/HIFα pathway may help us to develop new treatments for progressive cystic diseases of the kidney." (PMID 28934953, 2017).
Renal cyst (continued). "Therefore, the co-expression of Epo with EpoR in VHL-associated RCC and renal cysts suggests that a precursor cell of renal lesions is a developmentally arrested, pluripotent embryonic cell derived from nephrogenous mesenchyme." (PMID 23833638, 2013). "Notably, inactivation of Vhl in renal epithelial cells led to development of tubular cysts that share morphologic and molecular characteristics with renal cysts found in VHL patients." (PMID 19340311, 2009). "Notably, dedifferentiation has been observed in renal cysts following inactivation of VHL and changes in a number of renal cell differentiation markers have been observed in renal cysts." (PMID 17598890, 2007). "Moreover, loss of VHL function results in high levels of AURKA, affecting stability of the microtubular axoneme and leading to disassembly of the primary cilium followed by development of cystic kidneys and RCC." (PMID 38292052, 2023). "Despite many renal cysts, VHL individuals may preserve renal function." (PMID 35901549, 2022). "While renal cysts can be found in a population not carrying pVHL mutations, it is important to note that this could be evidence of progression of Type 2c VHL disease as individuals age." (PMID 36040300, 2022). "VHL inactivation causes renal cysts in mice and humans, but is not sufficient to cause ccRCC." (PMID 36106637, 2022). "In contrast to VHL, loss of Tsc1 or Tsc2 enhances cilia length in mouse MEF’s and zebrafish mutants, which could explain why TSC patients clinically exhibit few renal cysts and relatively low RCC frequency." (PMID 23628112, 2013). "In addition, other renal cystic disease-related genes, adenomatosis polyposis coli (APC) and Von Hippel-Lindau (VHL) are also directly targeted by c-Myc." (PMID 24349431, 2013). "Consequently, two studies have demonstrated the development of renal cysts when VHL is inactivated in tubular cells with or without consecutive deletion of PTEN, respectively." (PMID 22299048, 2012).
kidney tumors (35 papers, 2007 to 2025). "Recent research suggests that the annual growth rate of renal tumors in those with VHL deficiency is 0.37 cm/year, slightly lower than that observed in sporadic renal tumors (0.43 cm/year)." (PMID 39201746, 2024). "One of the patients with the VHL mutation developed metastasis of the pancreas (7 years after the primary kidney tumor) and was treated with Sunitinib (Sutent)." (PMID 37445575, 2023). "In our study, we investigated VHL, PTEN, and BAP1 genes and the sequencing of 24 samples of patients with renal tumors, revealing that VHL was mutated at a noticeable frequency (25%)." (PMID 37445575, 2023). "Previous studies have shown that HIF can mediate suppression of CDH1 gene transcription, and result in the downregulation of E-cadherin in VHL-deficient kidney tumor tissues." (PMID 37201027, 2023). "They studied the prevalence and clinical significance of VHL mutations and 3p25 deletions in renal tumor subtypes, and found highly variable ratios of VHL mutations and 3p deletions in the different histological subtypes of kidney tumors." (PMID 35205407, 2022). "In summary, our data show that VHL deletions and mutations occur frequently in kidney tumors and are largely unrelated to clinical or pathological parameters." (PMID 32076485, 2020). "The large number of cancers in combination with a thorough review of all tumors according to the recently published WHO criteria enabled us to collect information on VHL mutations in classical kidney tumor types and also in newly defined entities." (PMID 32076485, 2020). "Kidney tumors harbor a myriad of genetic alterations, including mutation or loss of the VHL gene, a tumor suppressor which is a common occurrence in >90% of clear cell kidney cancer cases." (PMID 32492043, 2020). "In the rare disease of hereditary kidney cancer, germline VHL mutation leads to early-onset bilateral kidney tumors." (PMID 30355451, 2018). "NSS-bases approaches tomanagement of VHL-associated renal tumors, using a 3 cm tumor size thresholdfor recommendation of surgery, can provide good cancer control while preservingrenal function and minimizing interventions." (PMID 18695737, 2008). "Our understanding of the genotype-phenotype link in RCC is based on a thorough analysis of VHL mutations found in primary human kidney tumors." (PMID 18047741, 2007). "The described genetic polymorphism (rs779805) of VHL is also considered to be pathogenic and may contribute to the development of renal tumors." (PMID 37445575, 2023). "The majority of kidney tumor subtypes had – at least in some cases – VHL mutations." (PMID 32076485, 2020). "In this study, we took advantage of a cohort of more than 1,800 tumors recently reviewed according to the latest WHO classification criteria to study the combined impact of VHL mutations and deletions in kidney tumors of all types and to study the role of these alterations on clinical outcome." (PMID 32076485, 2020). "Indeed, TCGA kidney tumours with mutated VHL show increase in DNA methylation as compared to kidney tumors with wild-type VHL (P < 2 * 10−16 for all CpGs)." (PMID 30006568, 2018). "Sporadic renal tumours require spontaneous mutation of two wild type VHL alleles." (PMID 26448938, 2015). "In kidney tumor cells 786-0 cells (cells with a deletion of one base pair on exon 1 of the VHL gene), the proteasome inhibitor Z-Leu-Leu-Leu-CHO (MG-132) promotes apoptosis in tumor cells." (PMID 40225869, 2025). "Renal tumors in BHD are more indolent compared to those in VHL, with an observed growth rate averaging 0.11 cm/year." (PMID 39201746, 2024). "In this study, using a sequencing approach, we analyzed the mutations of VHL, PTEN, and BAP1 in 24 renal tumor specimens." (PMID 37445575, 2023). "A previous study in genetically engineered mouse models had found that MYC activation with CDKN2A deletion and VHL deletion together produce kidney tumors that closely resemble human clear cell RCC41." (PMID 33547292, 2021).
kidney tumors (continued). "Typically for VHL patients in the clinic, when renal tumors increase by 3 cm in diameter, partial or total nephrectomy is required." (PMID 32854260, 2020). "Early clinical trials have shown that VHL‐related kidney tumors regress in response to treatment with rapamycin, a direct target of inhibition of mTORC1." (PMID 30107094, 2018). "When comparing VHL-null cell lines with wild type VHL cell lines of renal tumor models, HDAC 1 expression was found to be upregulated in VHL-null cell lines." (PMID 27506904, 2016). "To assess the biological role of HDAC 1, we knocked down its gene expression in VHL-null renal tumor cell lines, and selected the clones that displayed the most efficient HDAC 1 protein knockdown." (PMID 27506904, 2016). "Mutations occurring on the VHL gene are a critical event leading to CCRCC development in both sporadic and hereditary forms of kidney tumors." (PMID 23178531, 2012). "The development of a non-invasive test utilizing readily available and transportable biofluids could provide a significant improvement in the management of VHL patients, improving early detection of kidney tumors and successful intervention." (PMID 39062684, 2024). "The VHL, PTEN, and BAP1 genes are often mutated in renal tumors." (PMID 37445575, 2023). "In August 2021 after our survey was completed, the FDA approved belzutifan for VHL-associated CNS, pancreas, and kidney tumors that require treatment but not immediate surgery." (PMID 36310638, 2022). "A total of 705/1,805 (39.1%) samples of renal tumors were successfully sequenced for VHL." (PMID 32076485, 2020). "Western blot analysis revealed that HDAC 1 was differentially expressed in renal tumor cell lines with wild type and non-functional VHL in vitro." (PMID 27506904, 2016). "Unlike the VHL gene in ccRCC, BHD mutation is rarely reported in sporadic renal tumours; hence the role of folliculin in sporadic RCC is unclear." (PMID 26448938, 2015). "Whereas tumorsin VHL, HPRC, and BHD twins are oftenmultifocal and involve the 2 kidneys, renal tumors in patients withHLRCC may be solitary." (PMID 18695737, 2008). "Rodents exposed to carcinogens can develop kidney tumors; however, the genetic defect involves the tumor suppressor gene Tsc-2 (tuberous sclerosis complex-2) rather than VHL and the animals display chromophilic rather than clear cell histology." (PMID 18047741, 2007). "The number of genes within a panel may be as few as six (e.g. BAP1, FH, FLCN, MET, SDHB, and VHL genes) though commercial genetic testing companies may offer larger gene panels (18–30 genes but including some for non-RCC kidney tumours;)." (PMID 38802529, 2024). "However, it is not known at yet how the presence or absence of RASSF1A in kidney tumor cells interacts with the VHL or other pathways of kidney tumorigenesis." (PMID 18822131, 2008). "VHL+/- heterozygous mice (created by the Walker laboratory, University of Texas M.D. Anderson Cancer Center, USA) are prone to vascular proliferative lesions of the liver but do not develop kidney tumors." (PMID 18047741, 2007). "Based on our studies, we assume that changes in VHL and PTEN genes are not significantly related to the pathological characteristics or survival of patients with renal tumors." (PMID 37445575, 2023).
kidney tumors (continued). "The VHL-/- 786-O cells depleted of EGLN3 grew tumors just as well as the control cells, suggesting that EGLN3 inhibition alone is not a good way to suppress kidney tumor growth." (PMID 24260413, 2013).
colorectal cancer (30 papers, 2009 to 2026). A primary or metastatic malignant neoplasm that affects the colon or rectum. "Mutations in the VHL gene are common in colorectal carcinoma and result in the accumulation of HIF1α, leading to tumor angiogenesis." (PMID 38769340, 2024). "von Hippel Lindau (VHL) gene mutations have been found in 10% of colorectal cancer." (PMID 34117220, 2021). "Among E3 ligases used in proteolysis-targeting chimeras (PROTACs), VHL was upregulated together with its E2-conjugating enzyme UBE2S in colorectal cancers." (PMID 41898804, 2026). "In summary, our study demonstrates that Curcumol inhibits colorectal cancer (CRC) progression by activating the VHL/HIF-1α pathway, suppressing glycolysis and lactate production, and improving tumor microenvironment." (PMID 41008845, 2025). "This study is the first to reveal that Curcumol suppresses the progression of colorectal cancer (CRC) by activating the VHL/HIF-1α signaling pathway, thereby significantly inhibiting hypoxia-driven glycolysis." (PMID 41008845, 2025). "While several studies have explored the link between the VHL gene and various cancers, the connection between the VHL gene and colorectal cancer (CRC) remains largely unexplored." (PMID 40005423, 2025). "In conclusion, this study systematically reveals for the first time that Curcumol inhibits glycolysis and colorectal cancer (CRC) progression by activating the VHL/HIF-1α signaling axis." (PMID 41008845, 2025). "For instance, the KRAS gene mutated exclusively with the PTEN, VHL, RB1, and EGFR genes in large intestine cancers with high statistical significance." (PMID 26212640, 2015). "Thus, additional experiments about protein expression and molecular mechanisms of VHL in colorectal cancer need to be elucidated." (PMID 40005423, 2025). "Thus, the objective of this study was to examine the clinical and prognostic implications of VHL gene expression in Korean patients with RC, as well as its correlation with the expression of other genes in colorectal cancer (CRC) using TCGA data." (PMID 40005423, 2025). "The VHL gene may play a role in colorectal cancer progression and clinical features, paving the way for future research." (PMID 40005423, 2025). "As MXRA5 is overexpressed in ovarian, lung and colorectal cancer 24, 25, 26, we studied MXRA5 expression in VHL‐defective ccRCC cell line (VHL−/−)." (PMID 27599751, 2017). "The AI model failed to predict two genes, EPCAM (in a patient with colorectal cancer) and VHL (in a patient with acute lymphocytic leukemia (ALL) and Ewing sarcoma)." (PMID 38021917, 2023). "LncRNA-p21 is a hypoxia-responsive lncRNA that induces HIF-1α accumulation by integrating HIF-1α and Von Hippel–Lindau tumor suppressor (VHL), thus interrupting the VHL–HIF-1α interaction, which promotes glycolysis under hypoxic conditions in colorectal cancer cells." (PMID 33664256, 2021). "More intriguingly, the stabilization of pVHL by targeting CDK1 could also be a common regulatory mechanism in various types of cancer cells harboring wild-type VHL, including TNBC, pancreatic cancer, colorectal cancer and ovarian cancer." (PMID 36813923, 2023). "MZ1 degrades BRD4 in colorectal cancer cell lines resistant to the BET degrader dBETi, which hijacks cereblon and not VHL." (PMID 36046113, 2021).